TRBV6-1 (T cell receptor beta variable 6-1)
Description:
V region of the variable domain of T cell receptor (TR) beta chain that participates in the antigen recognition. Alpha-beta T cell receptors are antigen specific receptors which are essential to the immune response and are present on the cell surface of T lymphocytes. Recognize peptide-major histocompatibility (MH) (pMH) complexes that are displayed by antigen presenting cells (APC), a prerequisite for efficient T cell adaptive immunity against pathogens. Binding of alpha-beta TR to pMH complex initiates TR-CD3 clustering on the cell surface and intracellular activation of LCK that phosphorylates the ITAM motifs of CD3G, CD3D, CD3E and CD247 enabling the recruitment of ZAP70. In turn ZAP70 phosphorylates LAT, which recruits numerous signaling molecules to form the LAT signalosome. The LAT signalosome propagates signal branching to three major signaling pathways, the calcium, the mitogen-activated protein kinase (MAPK) kinase and the nuclear factor NF-kappa-B (NF-kB) pathways, leading to the mobilization of transcription factors that are critical for gene expression and essential for T cell growth and differentiation. The T cell repertoire is generated in the thymus, by V-(D)-J rearrangement. This repertoire is then shaped by intrathymic selection events to generate a peripheral T cell pool of self-MH restricted, non-autoaggressive T cells. Post-thymic interaction of alpha-beta TR with the pMH complexes shapes TR structural and functional avidity.
Synonyms: TRBV61; TCRBV13S3; TCRBV6S1
Gene: T-cell receptor variable (V) gene on chromosome 7 (142,328,297 to 142,328,786, forward strand). Ensembl gene ENSG00000211706.
Subcellular location: Cell membrane
Gene Ontology:
Biological process: cell surface receptor signaling pathway
Cellular component: plasma membrane
Homologues: Orthologues: macaque TRBV6-1 (89% identical). Paralogues in human: TRBV6-2 (84% identical), TRBV6-8 (84% identical), TRBV6-5 (82% identical), TRBV6-6 (82% identical), TRBV6-7 (82% identical), TRBV6-4 (71% identical), TRBV10-2 (58% identical), TRBV10-3 (57% identical), TRBV10-1 (56% identical), TRBV27 (56% identical), TRBV28 (54% identical), TRBV19 (52% identical), and 39 more.